HOXC9 (homeobox C9)
Description:
Sequence-specific transcription factor which is part of a developmental regulatory system that provides cells with specific positional identities on the anterior-posterior axis.
Synonyms: HOX3B; HOX3
Tractability: No criterion of Open Targets' tractability assessment is met for any kind of drug.
Gene: Protein-coding gene on chromosome 12 (53,994,895 to 54,003,337, forward strand). Ensembl gene ENSG00000180806.
Subcellular location: Nucleus
Subcellular location (Human Protein Atlas): Nucleoplasm
Gene Ontology:
Molecular function: protein binding; sequence-specific double-stranded DNA binding; DNA-binding transcription factor activity; DNA-binding transcription factor activity, RNA polymerase II-specific; RNA polymerase II cis-regulatory region sequence-specific DNA binding; DNA binding
Biological process: anterior/posterior pattern specification; embryonic skeletal system morphogenesis; negative regulation of cell cycle; proximal/distal pattern formation; regulation of transcription by RNA polymerase II; DNA-templated transcription; regulation of DNA-templated transcription
Cellular component: nucleoplasm; transcription repressor complex; chromatin; nucleus
Genetic constraint (gnomAD): Loss-of-function variants: 10 observed, 18.17 expected, observed/expected ratio (o/e) 0.55, 90% interval 0.34 to 0.93. The synonymous counts are far from expectation, so gnomAD's model fits this gene poorly and the ratio says little. Missense variants: 394 observed, 365.09 expected, observed/expected ratio (o/e) 1.08, 90% interval 0.99 to 1.17. Synonymous variants: 200 observed, 161.23 expected, observed/expected ratio (o/e) 1.24, 90% interval 1.11 to 1.39.
Homologues: Orthologues: chimpanzee HOXC9 (100% identical), macaque HOXC9 (99% identical), mouse Hoxc9 (99% identical), pig HOXC9 (99% identical), rat Hoxc9 (99% identical), rabbit HOXC9 (99% identical), tropical clawed frog hoxc9 (84% identical), zebrafish hoxc9a (72% identical). Paralogues in human: HOXD9 (56% identical), HOXB9 (48% identical), HOXA10 (37% identical), HOXD10 (35% identical), HOXC10 (32% identical), HOXC12 (27% identical), HOXA3 (25% identical), GSX2 (24% identical), PDX1 (24% identical), HOXC11 (24% identical), HOXD12 (24% identical), HOXA6 (23% identical), and 30 more.
Diseases named in the same sentence as HOXC9 in open-access papers:
HOXC9 is named in the same sentence as 41 diseases in open-access papers, as found by Europe PMC text mining. Sharing a sentence is not in itself a finding about the gene and the disease. The quoted sentences say what the papers report.
neuroblastoma (15 papers, 2012 to 2026). Neuroblastoma (NB) is the most common solid, extracranial childhood tumor. "HOXC9 expression has been associated with spontaneous regression of neuroblastoma and is a positive prognostic marker for survival." (PMID 37532697, 2023). "HOXC9 upregulation induced by retinoic acid (RA) can cause growth arrest and neuronal differentiation in neuroblastoma cells by upregulating neuronal differentiation genes and downregulating cell cycle promoting genes." (PMID 31013831, 2019). "In agreement with these experimental data, we found that higher HOXC9 mRNA expression is significantly associated with higher KDM6B mRNA expression in primary neuroblastoma tumors." (PMID 30631055, 2019). "In comparison with these HOX genes, increased HOXC9 expression is associated with neuroblastoma differentiation and better prognosis in neuroblastoma patients." (PMID 31013831, 2019). "Particularly, downregulation of HOXC9 expression is significantly associated with poor prognosis in neuroblastoma patients." (PMID 24274069, 2013). "We have recently reported that high-level HOXC9 expression is associated with neuroblastoma differentiation and is prognostic for better survival in neuroblastoma patients." (PMID 22879880, 2012). "Using neuroblastoma cell differentiation as an experimental system, we delineate a molecular mechanism by which HOXC9 coordinates diverse cellular processes associated with differentiation by directly activating and repressing the transcription of distinct sets of genes." (PMID 24274069, 2013). "Conforming to a pro-differentiation role for Hox genes, overexpression of HoxC9 in neuroblastoma cells and xenograft models, resulted in reduced growth potential in these cells and/or tumours." (PMID 41535654, 2026). "As such, elevated levels of HoxC9 correlated with improved prognosis and better survival in neuroblastoma patients." (PMID 41535654, 2026). "HOXC9, which acts as a regulator of cell proliferation and cycle related gene expression and as a mediator of RA action in neuroblastoma cells, was the second most highly enriched motif in the right-biased DARs." (PMID 35345851, 2022). "The activation of apoptosis pathway following increased expression levels of HOXC9 was significantly correlated with spontaneous regression in infant neuroblastoma." (PMID 34617205, 2022). "In infant neuroblastoma, HOXC9 significantly triggers the intrinsic apoptosis pathway via releasing cytochrome c (Cyt c) into the cytosol." (PMID 34617205, 2022). "Taken together, these data provide evidence for KDM6B as a direct transcriptional target gene of HOXC9 in RA-induced neuronal differentiation of neuroblastoma cells." (PMID 30631055, 2019). "HOXC9 is induced by RA and is a major downstream mediator of RA action, and HOXC9 overexpression is sufficient to induce neuronal differentiation of neuroblastoma cells." (PMID 30631055, 2019). "We used shRNA lentiviral constructs to reduce KDM6B mRNA and protein expression in neuroblastoma cell lines with inducible HOXC9 expression." (PMID 30631055, 2019). "Binding sites for HOXC9 (in neuroblastoma cells) and HOXC6 (in prostate cancer cells) have been identified using an antibody to a tagged, exogenously expressed protein." (PMID 30866492, 2019). "We have shown previously that HOXC9 is a major mediator of RA action in inducing neuroblastoma cell differentiation." (PMID 30631055, 2019). "We recently identified an RA-HOXD8-HOXC9 axis in driving neuroblastoma cell differentiation:38–40 RA induces HOXD8, which, in turn, transcriptionally activates HOXC9 expression." (PMID 30631055, 2019). "In line with previously published analyses of HOXC9 in neuroblastoma cells, we found a significant up-regulation of genes involved in neuronal differentiation pathways such as DNER, NEFL, DBH, TH, RET, MAP2 and NPY." (PMID 25406647, 2014). "We addressed this question in a model system of neuroblastoma cell differentiation induced by HOXC9." (PMID 24274069, 2013).
neuroblastoma (continued). "Together, these analyses demonstrate that HOXC9 activates a large number of neuronal genes, providing the molecular mechanism for its ability to induce neuronal differentiation of neuroblastoma cells." (PMID 24274069, 2013). "HOXD8 directly activates the transcription of HOXC9, a key effector of RA action in neuroblastoma cells." (PMID 22879880, 2012). "HOXC9 induces the growth arrest and neuronal differentiation of neuroblastoma cells by directly targeting both cell cycle-promoting and neuronal differentiation genes." (PMID 22879880, 2012). "We further present evidence that HOXC9, also a key mediator of RA action in neuroblastoma cells, is a direct target gene of HOXD8." (PMID 22879880, 2012). "Hoxc9 may act as a tumor suppressor and upregulated Hoxc9 may activate the intrinsic apoptosis signaling pathways in neuroblastoma cells." (PMID 33402862, 2020). "HOXC9 can induce neuronal differentiation of neuroblastoma cells." (PMID 31676945, 2020). "Moreover, our results from survival analyses reveal the prognostic value of PBX1, NF1, and HOXC9 expression in neuroblastoma tissue." (PMID 31803613, 2019). "In addition, we found that HOXC9 is up-regulated, a well described key regulator of neuroblastoma differentiation which links the intrinsic pathway of apoptosis, cell-cycle exit and neuronal differentiation." (PMID 25406647, 2014). "Among them, HOXC9 appeared to be a major mediator of RA action in neuroblastoma cells." (PMID 24274069, 2013). "Importantly, ectopic HOXC9 expression alone was sufficient to induce growth arrest and morphologic differentiation in neuroblastoma cells, fully recapitulating the neuronal differentiation phenotype induced by RA." (PMID 24274069, 2013). "In addition to HOXC9, it has been reported that RA treatment of neuroblastoma cells leads to a significant induction of several HOXD genes." (PMID 22879880, 2012). "Thus, myc-tagged HOXC9 binds to cognate sequences in human neuroblastoma cells." (PMID 24274069, 2013). "In neuroblastoma, KDM6B is upregulated by retinoic acid via HOXC9 to remove the repressive chromatin marker H3K27me3 and induce neuronal differentiation, thus inhibiting cell proliferation and tumorigenicity." (PMID 35783266, 2022). "In addition to the prognostic importance of PBX1, NF1, and HOXC9 proteins, our results demonstrated that PBX1 could be used for the prediction of the clinical response to induction chemotherapy in patients suffering from high-risk neuroblastoma." (PMID 31803613, 2019). "Importantly, our study further demonstrated that within the same population of neuroblastoma cells, HOXC9 could simultaneously activate the genes that promote neuronal differentiation and repress the genes that are essential for cell cycle progression and the DNA damage response." (PMID 24274069, 2013). "KDM6A expression was not correlated with the differentiation state of neuroblastoma tumors and was not upregulated during neuronal differentiation of neuroblastoma cells induced by RA or HOXC9." (PMID 30631055, 2019). "We noticed that HOXC9 knockdown alone led to a significant decrease in KDM6B mRNA levels in the absence of RA treatment, indicating an essential role of HOXC9 in maintaining the steady-state level of KDM6B mRNA expression in neuroblastoma cells." (PMID 30631055, 2019). "Finally, HOXD8 is a mediator of RA action in neuroblastoma cells by transcriptional activation of the HOXC9 gene, suggesting an RA-HOXD8-HOXC9 pathway in driving neuroblastoma cell differentiation." (PMID 22879880, 2012). "In addition, we show that KDM6B functions downstream of the retinoic acid-HOXC9 axis in inducing neuroblastoma cell differentiation: KDM6B expression is upregulated by retinoic acid via HOXC9, and KDM6B is required for HOXC9-induced neuroblastoma cell differentiation." (PMID 30631055, 2019).
breast carcinoma (9 papers, 2014 to 2024). "For instance, in breast cancer cell lines, HOXC9 overexpression curtailed cell proliferation while bolstering invasive capabilities, akin to promoting a phenotypic shift from proliferation to invasiveness." (PMID 38446596, 2024). "HOXC9 overexpression enhances invasiveness but decreases proliferation in various breast cancer cell lines." (PMID 37915086, 2023). "HOXC9 is upregulated in breast cancer, whose downregulation suppresses tumor cell proliferation and invasiveness." (PMID 32927434, 2020). "The role of HOXC9 in indicating better patient outcome was also supported by other studies on glioblastoma and breast carcinoma." (PMID 31188873, 2019). "However, a possible tumor suppressor role has also been reported in other studies, where overexpression of HOXC9 leads to decreased growth of nasopharyngeal carcinoma and stem cell properties in breast cancer cells." (PMID 32366326, 2020). "HOXC9 is aberrantly expressed in breast cancer, lung cancer, body fat mass and astrocytoma." (PMID 31676945, 2020). "Studies confirming this hypothesis are for example observations made in breast cancer cell lines in which overexpression of Homeobox Protein C9 (HOXC9) resulted in increased invasiveness but at the same time inhibited proliferation." (PMID 30123089, 2018). "We demonstrated that the expression of adipogenesis-related genes HOXC8, HOXC9, FABP4 and HSL in adipose tissue adjacent to malignant breast tumors was down-regulated and the level of inflammatory cytokines, like TNFα and MCP-1, was up-regulated." (PMID 25291184, 2014). "Homeobox C9 (HOXC9), a member of the HOX family, surfaces with anomalous expression across various cancer cell lines and tissues such as colorectal cancer, gastric cancer, and breast cancer." (PMID 38446596, 2024).
gastric cancer (8 papers, 2015 to 2025). A primary or metastatic malignant neoplasm involving the stomach. "Conversely, high HOXC9 expression has been observed in human gastric cancer and non-small cell lung cancer (NSCLC)." (PMID 37915086, 2023). "HOXC9 overexpression can also promote the development of stem cell- and metastasis-like cells in gastric cancer cells." (PMID 37915086, 2023). "Over-expression of miR-26a in gastric cancer cells has suppressed HOXC9 levels and inverted its effects on self-renewal of CSCs." (PMID 34368145, 2021). "For example, miR-26a has been observed to be downregulated in gastric cancer and has been identified as regulating stemness in gastric CSCs by downregulating HOXC9." (PMID 33562727, 2021). "HOXC9 has been suggested to promote the CSC phenotype in gastric cancer cells in vitro, as observed by the downregulation of CSC-associated surface markers CD44 and EpCAM, and CSC-associated markers SOX2 and OCT-4, after the knockdown of HOXC9." (PMID 33562727, 2021). "This miRNA targets HOXC9, an up-regulated gene and a prognosticator of poor clinical outcome in gastric cancer." (PMID 34368145, 2021). "The expression of HOXC9 mRNA and HOXC9 protein in gastric cancer tissue was significalntly higher than that in non-gastric cancer tissue." (PMID 34386426, 2021). "However, some genes such as HOXC9, FNDC1, STRA6, KCNE2, PGA3 and KCNJ16 haven’t been reported in gastric cancer and their roles remain unknown." (PMID 25928635, 2015).
Obesity (6 papers, 2019 to 2024). Accumulation of substantial excess body fat. "HOXC9 expression is linked with loss of adipose tissue function and visceral fat distribution, resulting in obesity, but this gene may be important for the improvement of insulin resistance." (PMID 30678306, 2019). "Despite the shortcomings of the Fabp4-Cre-mediated Hoxc9 targeting, we found a genotype-phenotype association in male ATHoxc9-/- mice after HFD-induced obesity." (PMID 32610701, 2020). "Taken together, our data suggest a role of Hoxc9 in the development of obesity and the determination of fat depot-specific signatures, which may affect whole body glucose metabolism, insulin sensitivity, and energy expenditure." (PMID 32610701, 2020). "Researchers speculated HOXC9 had important function in development of human obesity." (PMID 35231067, 2022). "However, the precise mechanisms by which Hoxc9 may contribute to obesity, AT distribution, and function are not well understood." (PMID 32610701, 2020). "Nevertheless, our data did not exclude a role of Hoxc9 in the development of obesity, AT distribution, and adipocyte function." (PMID 32610701, 2020).
bladder cancer (3 papers, 2020 to 2024). "Both the mRNA and protein expression of HOXC9 were significantly higher in bladder cancer 5637 cells (multi-chemosensitive) as compared to resistant bladder cancer H-bc cells (multi-chemoresistant)." (PMID 37627900, 2023). "The HOXC9 influences the chemoresistance promoting effect of miR-193a-3p in bladder cancer cell lines and tumor-xenografted/nude mice through the regulation of the DNA damage response and oxidative stress pathways." (PMID 37627900, 2023). "The miR-193a-3p promoted multi-chemoresistance of bladder cancer by repressing HOXC9 expression." (PMID 37627900, 2023). "Furthermore, it promotes the development of bladder cancer by targeting HOXC9." (PMID 33510768, 2020).
glioma (3 papers, 2021 to 2025). A benign or malignant brain and spinal cord tumor that arises from glial cells (astrocytes, oligodendrocytes, ependymal cells). "Among the seven key genes (HOXD11, HOXC9, HOXC6, HOXA3, FBXO39, OTP, and HMGA2) consistently detectable in both normal astrocyte cell lines (SVG-P12) and glioma cell lines (U87, U251, LN229), tumor cell lines exhibited significantly upregulated expression compared to normal cell lines." (PMID 41049291, 2025). "However, the molecular mechanisms of HOXC11, HOXC9, ELF5, and HNF4A function in the development and progression of gliomas remain unclear and require further exploration in the future." (PMID 33503296, 2021).
lung carcinoma (3 papers, 2013 to 2024). "The results showed that knockdown of Hoxc9 expression caused lung cancer cell apoptosis, and this biological effect may be related to cell cycle S phase arrest." (PMID 38446596, 2024). "In CMT167 and LLC cells, Hoxc9 overexpression promoted increased migration of lung cancer cells and invasion of lung cancer cells." (PMID 38446596, 2024). "Overall, overexpression of Hoxc9 promotes lung cancer proliferation, colony formation, and tumor cell invasion and progression." (PMID 38446596, 2024). "Taken together, HOXC9 is an oncogene that drives tumorigenesis and progression in lung cancer and can lead to poor prognosis by activating cell proliferation and causing immune dysfunction." (PMID 38446596, 2024). "The functional of Hoxc9 overexpression in lung cancer was determined by in vitro cell experiments." (PMID 38446596, 2024). "Overexpression of Hoxc9 promoted lung cancer cell proliferation and colony formation." (PMID 38446596, 2024). "First, public data on HOXC9 in lung cancer immunotherapy cohort are missing." (PMID 38446596, 2024). "Subsequently, flow cytometry PI/Annexin V was used to analyze the effect of Hoxc9 knockdown on the apoptosis of CMT167 and LLC lung cancer cells." (PMID 38446596, 2024).
gastric adenocarcinoma (2 papers, 2021 to 2023). "A previous bioinformatics analysis revealed that HOXC genes (HOXC8, HOXC9, HOXC10, HOXC11, HOXC12, and HOXC13) might participate in pathogenesis of gastric adenocarcinoma." (PMID 37724126, 2023).
prostate carcinoma (2 papers, 2019 to 2026). A carcinoma that arises from epithelial cells of the prostate gland. "In human prostate cancer LNCaP cells, homeobox C9 (HOXC9) was identified as a common regulated target gene by dihydroxytestosterone and 1α,25-dihydroxyvitamin D3, but in opposite directions." (PMID 41752098, 2026).
brain cancer (1 paper, 2017). A primary or metastatic malignant neoplasm affecting the brain. "At least five of them (ARNT2, NEUROD1, NR1I2, HOXC9, NR4A2) are associated with brain cancer in previous studies." (PMID 29033978, 2017).
clear cell renal carcinoma (1 paper, 2021). A malignant epithelial neoplasm of the kidney characterized by the presence of lipid-containing clear cells within a vascular network. "Moreover, a decreased HOXC8 and HOXC9 genes expression, as a classical white adipocytes signature, has been detected in perirenal fat in patients with clear cell renal carcinoma when compared to healthy people, while TBX1, TMEM26, or CD137 expression was unchanged." (PMID 33800984, 2021).
colon cancer (1 paper, 2015). "For instance, HOXB6, HOXB8 and HOXC9 are dysregulated at various stages of colon cancer development." (PMID 25875824, 2015).
cyst (1 paper, 2018). A sac-like closed membranous structure that may be empty or contain fluid or amorphous material. "In addition Hoxc9,10,11−/− Hoxd9,10,11−/− mice, with homozygous mutation of six Hox genes, showed highly penetrant severe cyst formation, while mice with fewer Hox genes mutations also showed cysts but with lower penetrance." (PMID 29679048, 2018).
cystic kidneys (1 paper, 2018). "For example, Hoxc9,10,11−/− Hoxd9,10,11−/− mutants showed highly penetrant severely cystic kidneys, while several other Hox mutation combinations produced cystic kidneys with lower penetrance." (PMID 29679048, 2018). "Grossly cystic kidneys were observed in all surviving Hoxc9,10,11−/− Hoxd9,10,11−/− mutants (age 3–6 weeks) (Y’, BB’)." (PMID 29679048, 2018). "Additionally, in mice uniformly sacrificed at 2 months of age, 10–15% of the Hoxa9,10,11−/− Hoxc9,10,11+/−, and Hoxa9,10,11+/− Hoxc9,10,11−/−, and triple heterozygote Hoxa9,10,11+/− Hoxc9,10,11+/− Hoxd9,10,11+/− mice showed grossly cystic kidneys (X’, Y’)." (PMID 29679048, 2018).